KLHDC10 (kelch domain containing 10)
Description:
Substrate-recognition component of a Cul2-RING (CRL2) E3 ubiquitin-protein ligase complex of the DesCEND (destruction via C-end degrons) pathway, which recognizes a C-degron located at the extreme C-terminus of target proteins, leading to their ubiquitination and degradation. The C-degron recognized by the DesCEND pathway is usually a motif of less than ten residues and can be present in full-length proteins, truncated proteins or proteolytically cleaved forms. The CRL2(KLHDC10) complex specifically recognizes proteins with a proline-glycine (Pro-Gly) or an alanine tail (CAT tail) at the C-terminus, leading to their ubiquitination and degradation. The CRL2(KLHDC10) complex is involved in the ribosome-associated quality control (RQC) pathway, which mediates the extraction of incompletely synthesized nascent chains from stalled ribosomes: CRL2(KLHDC10) acts downstream of NEMF and recognizes CAT tails associated with stalled nascent chains, leading to their ubiquitination and degradation. Participates in the oxidative stress-induced cell death through MAP3K5 activation. Inhibits PPP5C phosphatase activity on MAP3K5. Acts as a regulator of necroptosis (By similarity).
Synonyms: KIAA0265; slim; PNAS-138
Tractability: PROTAC: ubiquitination databases record sites on it.
Gene: Protein-coding gene on chromosome 7 (130,070,534 to 130,135,720, forward strand). Ensembl gene ENSG00000128607.
Subcellular location: Nucleus; Cytoplasm
Subcellular location (Human Protein Atlas): Nucleoplasm
Pathways (Reactome):
Metabolism of proteins: Ribosome Quality Control (RQC) complex extracts and degrades nascent peptide
Gene Ontology:
Molecular function: protein binding; ubiquitin-like ligase-substrate adaptor activity
Biological process: rescue of stalled ribosome; ubiquitin-dependent protein catabolic process via the C-end degron rule pathway; positive regulation of stress-activated MAPK cascade; ribosome-associated ubiquitin-dependent protein catabolic process; protein ubiquitination
Cellular component: Cul2-RING ubiquitin ligase complex; cytoplasm; nucleus; cytosol
Genetic constraint (gnomAD): Loss-of-function variants: 12 observed, 36.77 expected, observed/expected ratio (o/e) 0.33, 90% interval 0.21 to 0.53. The upper end of that interval is the gene's LOEUF score, 0.53, which puts it in group 2 of 6, group 1 being the genes least tolerant of losing a copy. Missense variants: 291 observed, 444.59 expected, observed/expected ratio (o/e) 0.65, 90% interval 0.59 to 0.72. Synonymous variants: 150 observed, 165.11 expected, observed/expected ratio (o/e) 0.91, 90% interval 0.8 to 1.04.
Homologues: Orthologues: chimpanzee KLHDC10 (100% identical), dog KLHDC10 (99% identical), macaque KLHDC10 (99% identical), pig KLHDC10 (99% identical), mouse Klhdc10 (97% identical), rat Klhdc10 (97% identical), guinea pig KLHDC10 (90% identical), rabbit KLHDC10 (88% identical), tropical clawed frog klhdc10 (75% identical), zebrafish klhdc10 (73% identical), Caenorhabditis elegans Y67H2A.2 (29% identical). Paralogues in human: HCFC1 (24% identical), HCFC2 (23% identical), LZTR1 (21% identical), KLHDC1 (20% identical), KLHDC2 (20% identical), KLHDC3 (19% identical), RABEPK (17% identical), KLHDC4 (17% identical), FBXO42 (15% identical), KLHDC9 (14% identical).
Diseases named in the same sentence as KLHDC10 in open-access papers:
KLHDC10 is named in the same sentence as 5 diseases in open-access papers, as found by Europe PMC text mining. Sharing a sentence is not in itself a finding about the gene and the disease. The quoted sentences say what the papers report.
breast carcinoma (1 paper, 2019). "SK2 KD universally downregulated expression of CAPZA1 (inhibition of autophagy and EMT) and also decreased expression of NSUN3, ADPGK and KLHDC10 in prostate and ITGAV in breast cancer cell lines." (PMID 30971929, 2019).
colorectal cancer (1 paper, 2021). A primary or metastatic malignant neoplasm that affects the colon or rectum. "Exosomal hsa_circ_0004771 and circ-KLHDC10 were significantly upregulated in patients with colorectal cancer, suggesting that they may represent potentially novel diagnostic biomarkers for colorectal cancer." (PMID 33430880, 2021).
KLHDC10 also shares sentences with these, for which no sentence is quoted: cancer (1 paper); hepatocellular carcinoma (1); polycystic kidney disease (1).